FOS (Fos proto-oncogene, AP-1 transcription factor subunit)
Diseases named in the same sentence as FOS in open-access papers (continued):
Sharing a sentence is not in itself a finding about the gene and the disease.
deafness (2 papers, 2019). An inherited or acquired condition characterized by the complete loss of the ability to hear from one or both ears. "The expression of FOS was found to be dynamically changed after deafness, with lower level in the auditory cortex 15 days (compensation mechanism), but increased from 2 weeks and stabilized three months after permanent auditory deprivation in adult rats." (PMID 31149396, 2019).
encephalitis (2 papers, 2022 to 2025). An acute inflammatory process affecting the brain parenchyma. "Additionally, JUN and FOS bind to AP-1 sites in gene promoters, triggering transcriptional activation of cytokines involved in macrophage differentiation, as well as viral gene expression and progeny virus production in certain viral infections, such as lentivirus and encephalitis viruses." (PMID 40005815, 2025).
experimental autoimmune encephalomyelitis (2 papers, 2018 to 2025). An autoimmune demyelinating disease of the central nervous system that is produced experimentally in animals by the injection of homogenized brain or spinal cord in Freund's adjuvant. "In animal experiments, FOS transgenic mice were more resistant to experimental autoimmune encephalomyelitis by inhibiting the production of inflammatory cytokines in dendritic cells." (PMID 40585331, 2025).
fatty liver disease (2 papers, 2021 to 2025). A reversible condition wherein large vacuoles of triglyceride fat accumulate in liver cells via the process of steatosis. "Previous studies have indicated that the disorder of immune cells (Treg and Th17 cells) in fatty liver disease may be regulated by microRNA-29c by acting on the FOS gene, thereby regulating liver damage and fat deposition." (PMID 33927635, 2021).
gingivitis (2 papers, 2019 to 2021). A disorder involving inflammation of the gums; may affect surrounding and supporting structures of the teeth. "Among all of the 55 regulated genes (>2-fold, both up and down regulated), FOS is the only one that was up-regulated by commensal and gingivitis biofilms (2-fold) but down-regulated by cariogenic biofilm (2-fold)." (PMID 31448244, 2019).
hearing loss (2 papers, 2018 to 2019). "As a TF, FOS may participate in inflammation by regulating its target genes, such as ICAM-1, CSF1 and CCL5 which were all important inflammatory proteins for hearing loss." (PMID 31149396, 2019). "One factor that causes sensorineural hearing loss is noise and studies in mouse models have suggested that noise exposure activates the MAPK signaling pathway and the FOS gene among other genes is up-regulated in MAPK Signaling pathway." (PMID 29545597, 2018).
hypersomnia (2 papers, 2014 to 2018). A sleep disorder characterized by excessive sleepiness. "It has indeed been shown that, in rats, the DPGi contains a large population of neurons expressing c-FOS (a marker of neuronal activation) during PS hypersomnia." (PMID 24811249, 2014). "It has then been shown in rats that the DPGi contains the majority of neurons projecting to the LC and expressing c-FOS (a marker of neuronal activation) during PS hypersomnia." (PMID 24811249, 2014).
IgA Nephropathy (2 papers, 2016 to 2022). "Only PLAU, JUN, and FOS were related to DNA damage, telomere dysfunction-induced aging markers, neutrophil function and IgA nephropathy." (PMID 27127888, 2016). "By overlap, we found three genes, JUN, FOS, and PLAU were simultaneously participated in aging and inflammation, and were also previously reported to be related to IgA nephropathy." (PMID 27127888, 2016).
invasive breast carcinoma (2 papers, 2008 to 2012). A carcinoma that infiltrates the breast parenchyma. "To test this hypothesis, we compared the expression levels of FOS in 10 surgical specimens of invasive breast cancers that were left in an ischemic state for at least 30 minutes before freezing to our FNAB specimens." (PMID 18826606, 2008).
lipodystrophy (2 papers, 2013 to 2024). A congenital or acquired disorder characterized by abnormal loss or redistribution of the adipose tissue in the body. "In CGL cells, there is a sign of combined lipodystrophy-related genes with a pattern of downregulation of CAVIN1 and FOS." (PMID 38755198, 2024). "In addition, lipodystrophy-related genes were modulated: CAVIN1 (downregulated in infected AGPAT2mut vs. WT) and FOS (downregulated in AGPAT2mut and BSCL2mut vs. WT)." (PMID 38755198, 2024).
malaria (2 papers, 2016 to 2023). Malaria is a serious and sometimes fatal disease caused by a parasite that commonly infects a certain type of mosquito which feeds on humans. "Other genes previously associated with malaria pathogenesis, GZMB, FOS and HSPA6, were also higher among severe cases." (PMID 26961973, 2016). "Of the remaining probes, four were in three genes, HSPA6, TLR8 and FOS, previously identified in experiments for malaria severity in human or murine systems." (PMID 26961973, 2016). "This is the first study directly linking FOS expression levels to severe malaria in humans." (PMID 26961973, 2016). "Differentially expressed probes form these canonical pathways that were previously shown to play a role in severe malaria pathogenesis were TLR2, TLR4, TLR8, HSPA6, CR1, C1qA, C1qB, C1qC, FOS, and GZMB." (PMID 26961973, 2016). "The FOS and GZMB genes were also found to be expressed at elevated levels in severe malaria cases in this study (by 2.09- and 2.31-fold, respectively)." (PMID 26961973, 2016). "The higher expression of the TLR genes, GZMB, FOS, HSPA6, and CR1, in uncomplicated malaria cases during the late convalescence time point can be interpreted two ways." (PMID 26961973, 2016).
male infertility (2 papers, 2021 to 2025). The inability of the male to effect fertilization of an ovum after a specified period of unprotected intercourse. "The results showed that CREM, TBP, CREB1, HDAC1, and FOS had the most relationship with male infertility." (PMID 34400949, 2021).
non-alcoholic fatty liver disease (2 papers, 2021 to 2022). "Pathway analysis revealed that FOS was involved in the IL-17 signaling pathway, which impacts the nonalcoholic fatty liver disease process." (PMID 33927635, 2021). "This suggests that microRNA-29c acting on the FOS gene is closely related to the development of nonalcoholic fatty liver disease." (PMID 33927635, 2021). "This indicates that the action of the FOS gene is closely related to the development of nonalcoholic fatty liver disease." (PMID 33927635, 2021).
orofacial cleft (2 papers, 2022 to 2023). A disorder of facial skeleton that is characterized by cleft lip and/or cleft palate that result in feeding, speech and hearing problems caused by failures during development. "Together with the findings that variation in FOS is associated with NSCLP, these results suggest that altered fos expression affects the growth and shape of the oral cavity and midface regions and potentially plays an etiologic role in the development of an orofacial cleft." (PMID 37664458, 2023).
pancreatic ductal adenocarcinoma (2 papers, 2012 to 2026). An infiltrating adenocarcinoma that arises from the epithelial cells of the pancreas. "Using NetRank, we identified seven genes (STAT3, FOS, JUN, SP1, CDX2, CEBPA, and BRCA1) as most relevant for predicting survival in patients with pancreatic ductal adenocarcinoma." (PMID 22615549, 2012).
pneumonia (2 papers, 2017 to 2021). An acute, acute and chronic, or chronic inflammation focally or diffusely affecting the lung parenchyma, caused by an infection in one or both of the lungs (by bacteria, viruses, fungi, or mycoplasma.). "FOS may be an effective adjunctive therapy for pneumonia caused by MDR/XDR A. baumannii, considering the synergistic effect of COL and FOS in vitro." (PMID 29262831, 2017). "Among them, 23 target proteins such as PTGS2, TNF and FOS were enriched in the IL-17 signalling pathway, indicating that the IL-17 signalling pathway plays an important role in the treatment of pneumonia by RYNM." (PMID 33678123, 2021).
polycystic ovary (2 papers, 2021 to 2025). "Moreover, cold stress resulted in an increase in the number of FOS‐immunoreactive neurons in the locus coeruleus in polycystic ovary in rats." (PMID 34346538, 2021).
renal fibrosis (2 papers, 2022 to 2025). A final common manifestation of a wide variety of chronic kidney diseases characterized by glomerulosclerosis and tubulointerstitial fibrosis. "Consistent with the qRT-PCR results, the Western blot analysis results demonstrated that FOS may be the target gene for the FZHY decoction against renal fibrosis." (PMID 36569327, 2022). "Similarly, the results of the Western blot analysis demonstrated that FOS may serve as a target gene through which FZHY exerts its effects against renal fibrosis." (PMID 36569327, 2022).
rheumatic diseases (2 papers, 2019 to 2025). "Therefore, the aim of this study was to analyse SNPs in the core promoters of the proto-oncogenes JUN, JUNB, JUND, and FOS in patients with rheumatic diseases, to investigate their functional relevance, and to assess potential associations between these SNPs and the occurrence of RA or knee-OA." (PMID 30893847, 2019).
uremia (2 papers, 2021 to 2024). A clinical syndrome associated with the retention of renal waste products or uremic toxins in the blood. "The expression of FOS in VLPO neurons of the hypothalamus is linked to the activation of neurons that initiate sleep, and this expression is affected by uremia in CKD patients, resulting in sleep disturbances." (PMID 38751978, 2024).
Achalasia (1 paper, 2023). A disorder of esophageal motility characterized by the inability of the lower esophageal sphincter to relax during swallowing and by inadequate or lacking peristalsis in the lower half of the body of the esophagus. "Analysis of DEGs showed the upregulations of PPDPF, NENF, and CYBA and downregulations of FOS, DUSP1, and GPX1 in peripheral blood myeloid cells of achalasia." (PMID 37542039, 2023).
acute leukemia (1 paper, 2014). A clonal (malignant) hematopoietic disorder with an acute onset, affecting the bone marrow and the peripheral blood. "Several (i.e. CEBPB, FOS and FOSB) were also described to be deregulated in the transition of CML blastic phase to an acute leukemia." (PMID 24517546, 2014).
acute pancreatitis (1 paper, 2019). An acute inflammatory process that leads to necrosis of the pancreatic parenchyma. "Further studies should be performed exploring whether DHA affects RyR, IP3R, Relb, and c-FOS at post-transcriptional level and their functional roles involving the calcium network to determine the effect of DHA on cerulein-induced acute pancreatitis." (PMID 31248019, 2019).
adenomyosis (1 paper, 2020). The growth of endometrial tissue inside the muscular wall of the uterine corpus. "Isolated total RNA from endometrial biopsy samples collected during the window of receptivity were used to verify whether selected candidate genes LIF, SOCS3, FOS, JUNB, IL6 and IL10 were differentially expressed between adenomyosis and control groups." (PMID 32933042, 2020). "Despite LIF, IL6, IL10, JUNB, FOS and SOCS3 showing no statistically altered expression patterns between study groups, their lower expression levels were observed in the adenomyosis group." (PMID 32933042, 2020).
adrenal incidentalomas (1 paper, 2025). "•Oxidative stress drives spatial activation of FOS and JUN in peritumoral cortex of functional adrenal adenomas." (PMID 41412035, 2025). "In contrast, both total and phosphorylated forms of FOS and JUN were undetectable in normal adrenal cortex, as well as in both the tumor and adjacent cortex of non-functioning adrenal incidentalomas." (PMID 41412035, 2025).
adrenal tumors (1 paper, 2025). "•FOS and JUN couple redox imbalance with remodeling of adrenal tumor microenvironment." (PMID 41412035, 2025).
age (1 paper, 2024). A temporal measurement of the time period elapsed since an identifiable point in the life cycle of an organism. "The interplay between NFκB, PDGF-BB, LY6E, ID3, PTP4A1, and FOS in age-related vascular endothelial dysfunction and related pathologies underscores the complexity of molecular mechanisms governing vascular health." (PMID 38674087, 2024).
anaphylaxis (1 paper, 2023). An acute hypersensitivity reaction that occurs from exposure to an allergen. "Hub genes identified here (IL1R2, FOS, MMP9, DUSP1, and CLEC4D) represent a whole blood gene signature of anaphylaxis with STEMI predisposition and provide candidate diagnostic and therapeutic targets for follow-up studies." (PMID 37469874, 2023). "Inhibition of FOS expression by T-5224 attenuates IgE-mediated anaphylaxis." (PMID 37469874, 2023). "Taking the intersection of six algorithms (DMNC, Stress, MCC, Degree, Closeness, Radiality) in cytoHubba, we found 6 hub genes shared by anaphylaxis and STEMI: IL1R2, S100A12, FOS, MMP9, DUSP1, and CLEC4D." (PMID 37469874, 2023). "IL1R2, FOS, MMP9, DUSP1, and CLEC4D were screened and identified as hub genes shared by anaphylaxis and STEMI." (PMID 37469874, 2023). "In this study, we identified four approved drugs that have the potential to be repurposed against hub genes involved in anaphylaxis complicated STEMI, including anakinra, baclofen, andecaliximab, and albuterol targeting IL1R2, FOS, MMP9, and DUSP1, respectively." (PMID 37469874, 2023).
aortic aneurysm (1 paper, 2022). A ruptured aneurysm located in the wall of the proximal portion of the descending aorta proceeding from the arch of the aorta. "Additionally, increased levels of FOS have been shown in aortic aneurysm." (PMID 36187757, 2022).
avian influenza (1 paper, 2022). Infection of domestic and wild fowl and other birds with influenza A virus. "After the analysis of DEGs and hub genes, a total of three genes, namely EGR1, JUN and FOS, were screened, which have been reported to have a major role in the resistance of chickens to avian influenza." (PMID 36557693, 2022).
burn (1 paper, 2024). A traumatic injury involving interruption of tissue cohesiveness that results from exposure to caustic chemicals, extreme heat, extreme cold or excessive radiation. "Burn patients showed a decreased enrichment of H3K9me2 in CXCL8, IL-17, and TNFA promoters, whereas IL-6, FOS, and IL-1B promoters displayed an H3S28p enrichment diminution during the first 10 days post-burn." (PMID 39768289, 2024).
cardiac interstitial fibrosis (1 paper, 2024). "However, targeted FOS therapy has been shown to have the ability to improve cardiac function by ameliorating cardiac interstitial fibrosis after MI." (PMID 39086489, 2024).
cataract (1 paper, 2023). Partial or complete opacity of the crystalline lens of one or both eyes that decreases visual acuity and eventually results in blindness. "Compared with the ARC group, the levels of CTGF, FOS, CAV1, CYR61, ICAM1, EGR1, and NR4A1 in the anterior capsule of PACG patients with cataracts were upregulated, which was consistent with the sequencing data." (PMID 37131205, 2023).
chronic gastritis (1 paper, 2018). Inflammation of the stomach that is chronic in nature. "It seems that JUN and FOS are the two critical genes related to the chronic gastritis." (PMID 30425814, 2018).
clear cell carcinoma (1 paper, 2019). "Five most downregulated genes in clear cell carcinoma include, ITGB6 (−9.09-fold), MUC1 (−5.00-fold), CDH1 (−3.57-fold), HIF1A (−2.27-fold) and FOS (−1.96-fold)." (PMID 30863721, 2019).
cleft lip (1 paper, 2022). Congenital defect in the upper lip where the maxillary prominence fails to merge with the merged medial nasal prominences. "The aim of this study was to evaluate single nucleotide polymorphisms (SNPs) in FOS, CASP8 and MMP2 and to determine their SNP-SNP interactions with CRISPLD2 variants in the risk of nonsyndromic cleft lip with or without cleft palate (NSCL±P) in the Brazilian population." (PMID 36661544, 2022).
colon adenocarcinoma (1 paper, 2021). "In contrast, colon adenocarcinoma showed a significant enrichment of TFs such as CDX2 (26.5%), CDX1 (24%), HOXA13 (22%), HNF4G (37.2%), and TCF4 (36%) in gained peaks; and FOS::JUNB (45.4%), FOS::JUND (47.5%) and JUNB (46.3%) in lost peaks." (PMID 34090364, 2021).
corneal disease (1 paper, 2023). "FOSL1, along with FOSL2, a novel candidate for corneal disease in our study, and other TFs from the FOS and JUN families, are known to be important in epidermal cells." (PMID 37856539, 2023).
deep vein thrombosis (1 paper, 2024). "This is also consistent with the significant downregulation of FOS in deep vein thrombosis." (PMID 38818568, 2024). "Therefore, we investigated whether FOS is a hub immune‐related gene involved in deep vein thrombosis and explored its potential mechanisms of action." (PMID 38818568, 2024).
diabetic neuropathy (1 paper, 2019). A chronic, pathological complication associated with diabetes mellitus, where nerve damages are incurred due to diabetic microvascular injury involving small blood vessels that supply these nerves, resulting in peripheral and/or autonomic nerve dysfunction. "On the other hand, changes in FOS expression in diabetic neuropathy and other stressful events including hypoxia–ischemia suggest a neuro-protective role for FOS expression." (PMID 31728912, 2019).
diabetic retinopathy (1 paper, 2014). "Only 3 studies in the STZ and non-insulin-dependent diabetic rat models have evaluated the consequences of diabetic retinopathy on light-induced FOS protein in the SCN." (PMID 25006976, 2014).
diffuse astrocytoma (1 paper, 2016). A low-grade (WHO grade II) astrocytic neoplasm. "The AP-1 transcription factors FOS and FOSL1 were found to be significantly up-regulated in the pilocytic astrocytomas compared to diffuse astrocytomas and normal brain controls." (PMID 27229157, 2016).
dilated cardiomyopathy (1 paper, 2024). Cardiomyopathy which is characterized by dilation and contractile dysfunction of the left and right ventricles. "GATA4 is a critical regulator of cardiac differentiation; FOG2/ZFPM2 is essential for heart morphogenesis and coronary development; FOS is significantly activated in dilated cardiomyopathy." (PMID 38474301, 2024).
dry eye (1 paper, 2024). "Increased transcriptional activity of FOS, JUN and ELK have been previously linked to activation of IL1b signaling, further implicating this pathway as a key driver of keratocyte inflammation in dry eye." (PMID 39677756, 2024).
E. coli infection (1 paper, 2024). "In this study, E. coli infection up-regulated key genes in the Th17 cell differentiation pathway, including FOS, VEGFA, IL12RB2, IFN-ALPHA-8, and IFN-ALPHA-13, indicating widespread activation of the immune system." (PMID 39707535, 2024). "Protein network analysis indicated that genes such as FOS, CTLA4, APOA1, CEL, FRK, and AGTR1 had the strongest association with other genes, highlighting their crucial roles in E. coli infection." (PMID 39707535, 2024).
estrogen-receptor positive breast cancer (1 paper, 2022). "Analyses of The Cancer Genome Atlas data indicated that higher ATF3, FOS, and FOSB expression levels correlated with low HSF1 levels in estrogen receptor-positive breast cancer, reflecting higher heat shock-induced expression of these genes in HSF1-deficient MCF7 cells observed in vitro." (PMID 36010586, 2022).
Fanconi anemia (1 paper, 2023). Fanconi anemia (FA) is a hereditary DNA repair disorder characterized by progressive pancytopenia with bone marrow failure, variable congenital malformations and predisposition to develop hematological or solid tumors. "Among these 14 pathways, four major pathways were enriched: SNARE interactions involved in the vesicular transport (BET1 and STX6), leishmaniasis (FCGR1A, CYBB, and FOS), hematopoietic cell lineages (FCGR1A, ITGA3, MME, and CD5) and Fanconi anemia pathway (SLX4, ATR, and TELO2)." (PMID 37601105, 2023).